PPARG (peroxisome proliferator activated receptor gamma)
Diseases named in the same sentence as PPARG in open-access papers (continued):
Sharing a sentence is not in itself a finding about the gene and the disease.
Insulin resistance (continued). "In the REVERT trial, short-term rosiglitazone therapy significantly lowered insulin resistance, high sensitivity C-reactive protein (hsCRP), and von Willebrand factor (vWF), suggesting that PPARγ agonists may reduce endothelial dysfunction in patients with CKD." (PMID 25371664, 2014). "Therefore, by activating PPARα, PPARδ, and PPARγ together and reducing TG in skeletal muscles, bezafibrate might improve glucose intolerance and insulin resistance in skeletal muscle." (PMID 25360162, 2014). "The fact that PPARγ facilitates the maintenance of normal insulin sensitivity leads to the conclusion that its inhibition by TNFα could possibly account for TNFα-induced insulin resistance." (PMID 24324517, 2013). "In addition, it has been postulated that PPARγ may have an effect on lipid metabolism, insulin resistance, and insulin secretion by inducing the transcription of target genes." (PMID 23991018, 2013). "However, the relationship between PPARγ or RBP4 polymorphism and insulin resistance or dyslipidemia in HIV-infected patients receiving HAART remains unclear." (PMID 23145084, 2012). "In addition, another study also demonstrates that mice deleted for PPARγ, a nuclear receptor involved in adipocyte differentiation and macrophage M2 alternative polarization, displayed insulin resistance with reduced number and impaired function of M2 macrophages." (PMID 20877467, 2010). "Therefore the synergistic effects of PPARγ and the HO system in improving insulin sensitivity and glucose metabolism may be a novel approach to combat insulin resistance and related cardiometabolic complications." (PMID 20508722, 2010). "In light of those results, PPARγ agonists appear to becompelling drugs for the prevention of liver injury related to insulin resistance.PPARα could be involved in fibrogenesis through adiponectin activation, as thisadipokine could have antifibrogenic properties." (PMID 19390649, 2009). "Interestingly, the variants in PPARG, ADIPOQ, and ENPP1, which elevate risk in obese populations, have been categorized as acting on insulin resistance while the TCF7L2 variant elevating risk in lean populations has been categorized as acting on insulin secretion." (PMID 18498634, 2008). "The gene expression of PPARγ and its target genes CD36, LDL in whitefat tissue, and PPARα and its target gene ACO in liver were also elevated in CE-treatedDIO mice indicating that CE may act as a dual activator of PPARγ and PPARαresulting in improved insulin resistance and lowered serum lipids." (PMID 19096709, 2008). "It remainsunclear however, as to whether these abnormalities are simply a“metabolic consequence” of severe insulin resistance per se, or whether they indicate an additive and independent effectof dysfunctional PPARγ signalling in relation tolipoprotein metabolism." (PMID 17389771, 2007). "Additionally, irbesartan restores mitochondrial bioenergetics by increasing levels of oxidative phosphorylation complexes (OXPHOS) and improving insulin resistance, which could be related to its function as a selective modulator of peroxisome proliferator-activated receptor gamma (PPARγ)." (PMID 40868980, 2025). "Thirteen overlapping targets between the gut microbiota and insulin resistance were identified, among which IL6, JUN, and PPARG were recognized as hub genes." (PMID 40625623, 2025). "Activation of PPARγ has been shown to ameliorate NASH in preclinical models by reducing hepatic inflammation, oxidative stress, and insulin resistance." (PMID 40994455, 2025). "PPARγ is key in NAFLD development, affecting lipid buildup, insulin resistance, inflammation, oxidative and ER stress, and fibrosis, making it a potential treatment target." (PMID 40994455, 2025). "In rats, PMG enhanced metabolic parameters by lowering body weight, plasma glucose levels, and inflammatory cytokines while simultaneously boosting peroxisome proliferator-activated receptor gamma (PPAR-γ), lipid profiles, and insulin resistance." (PMID 39347133, 2024).
Insulin resistance (continued). "The hypermethylation positively correlated with the insulin resistance stage (assessed by HOMA-IR) and negatively with the expression of PPARG." (PMID 39595621, 2024). "This dysregulation of PPARγ and its downstream targets of GLUT-4 by exosomes contributed to in vivo and in vitro insulin resistance and glucose intolerance." (PMID 39063184, 2024). "PPARγ agonists such as troglitazone (Rezulin), pioglitazone (ACTOS), and rogradone (Avandia) reduce insulin resistance, hyperinsulinemia, and hyperglycemia in diabetics." (PMID 38925330, 2024). "Our findings demonstrate that MCTs can partially activate PPARγ and inhibit the CDK5-mediated phosphorylation of PPARγser273, thereby ameliorating hyperglycemia and insulin resistance while restoring glucose homeostasis in obese rats." (PMID 38254542, 2024). "Variants within this cluster mapped to genes with known effects on insulin resistance, including IGF2, INSR, KLF14, and PPARG in adipose tissue." (PMID 38200577, 2024). "At the same time, this paper further explored the molecular mechanism of 3HB decreasing insulin resistance level, which is by indirectly inhibiting the phosphorylation of PPARγ Ser273 site through HCAR2/Ca2+/cAMP/PKA/Raf1/ERK1/2/PPARγ signaling pathway." (PMID 37230992, 2023). "Previous studies using selective PPARγ activators, including SR1664, suggested that these agents are effective in improving insulin resistance through their insulin-sensitizing effects." (PMID 37886997, 2023). "PPARγ/SREBP-1c pathways are involved in alleviation of Antrodan-treated NAFLD via upregulated pAMPK and Sirt1, and downregulated PPARγ and SREBP-1c, thereby suppressing lipid biosynthesis and facilitating insulin resistance." (PMID 36552896, 2022). "The PPARα and PPARγ vastly function to reduce inflammation, while PPAR-beta(β) is a potential target for the treatment of insulin resistance." (PMID 36164476, 2022). "Therefore, high PPARG exon 5 deletion SV levels in the GCs of obese individuals may account for the reduced transcription of metabolic genes and the impaired lipid metabolism in these individuals, which are strictly correlated with insulin resistance." (PMID 36555903, 2022). "With regard to TZD (PPARγ agonists), their use for treating NAFLD has been reported to improve steatosis, inflammation, fibrosis, and insulin resistance, and the AASLD and EASL guidelines recommend their use in patients with NASH." (PMID 35277054, 2022). "SAB regulated insulin resistance mainly through the AMPK/GLUT4 and/or SREBP-1/PPARγ signaling pathway, and modulated fatty acids through PPAR-mediated pathways, and exerted the effect of anti-inflammatory by STRT1/chREBP." (PMID 35528835, 2022). "Ultimately, these results suggest that systemic application of a potent PPARγ agonist (namely, TZD) overrides the metabolic effects of insulin resistance and glucose intolerance of PPARγ acetylation in macrophages." (PMID 37213714, 2022). "Peroxisome proliferator-activated receptor gamma (PPAR-γ) is mainly involved in lipid and glucose metabolism, and its activation is thought to promote insulin resistance." (PMID 36295866, 2022). "Insulin resistance analysis reveals that both OCA and Fer-1 significantly increase the serum level of PYY and the relative expression of PPARγ in the liver." (PMID 36588706, 2022). "Studies on synthetic PPAR antagonist showed that blocking or reducing the activity of PPARγ can reduce HFD-induced adipocyte hypertrophy and insulin resistance by reducing the size of adipocytes and decreasing the secretion of TNF-α and leptin." (PMID 34721992, 2021). "Retinaldehyde (retinal), the oxidized product of retinol, has been thought to act as an inhibitor for the PPARγ/RXR action in fat cells and improve insulin resistance in ob/ob mice." (PMID 34440929, 2021).
Insulin resistance (continued). "Local inflammation due to residential macrophages plays a key role in liver insulin resistance due to HFD diet consumption, exemplified by increased TNF-α and synchronously reduced PPARγ expression in HFD-fed mice in this study." (PMID 34803738, 2021). "Brd4 occupied the promoter and enhancers of Gdf3 to facilitate PPARγ-dependent expression of Gdf3, which in turn suppressed ATGL expression and lipolysis in adipocytes, resulting in the increased fat accumulation and insulin resistance." (PMID 33830083, 2021). "PPARγ regulates CD36 expression by virtue of a PPARγ responsive element in the proximal region of CD36 promoter, and CD36 deficiency reduces fatty acid uptake and may lead to insulin resistance, which indicates CD36 is metabolically protective in adipose and muscle tissues." (PMID 34440852, 2021). "Vitamin D regulates the metabolism of free fatty acids (FFAs) through its action on peroxisome proliferator-activated receptor gamma (PPAR-γ), improving FFA-induced insulin resistance in vitro." (PMID 34680475, 2021). "An in vivo study with diabetic mice showed that the use of sodium selenate increased the expression of peroxisome proliferator-activated receptor gamma (PPAR-γ), which acts on insulin resistance and increases lipid metabolism." (PMID 34490321, 2021). "Through the activation of PPARγ, TZD can reduce insulin resistance, sequester fatty acid in adipose tissue, and alleviate fat storage, steatosis and ballooning in the liver." (PMID 31960563, 2020). "Paradoxically, exacerbation of systemic insulin resistance, adiposity, and hyperlipidemia against reduced hepatic steatosis in diabetic PpargΔHEP mice corroborated that liver PPARγ protects other tissues from TAG accumulation and insulin resistance." (PMID 32192216, 2020). "Vitamin D affects adipogenesis by regulating the expression of adipocyte transcription factors, such as PPARγ, C/EBPα, and LPL, and through affecting insulin resistance, VDR and unliganded VDR, and adipokine secretion." (PMID 32149047, 2020). "PPARγ is well known as a regulator of insulin sensitivity and TZD drugs ameliorate insulin resistance by reducing plasma glucose and they improve the lipidemic profile in type 2 diabetes (T2D) and in obese subjects without diabetes." (PMID 33198317, 2020). "Pioglitazone is a thiazolidinedione (TZD), targeting the peroxisome proliferator-activated receptor gamma (PPAR-γ), that can reduce insulin resistance and hepatic gluconeogenesis." (PMID 33172034, 2020). "In a mouse model of HFD-induced insulin resistance, elevating PPARγ acetylation reduced the browning of WAT via inhibiting recruitment of SIRT1 to PPARγ." (PMID 31336903, 2019). "In this scenario, SR-B1 acts in a peroxisome proliferator-activated receptor gamma (PPARγ)-dependent manner, which coincides with other research regarding PPAR’s role in the regulation of lipid metabolism and insulin resistance." (PMID 32922929, 2019). "Non-clinical studies have shown that azilsartan increases the expression of PPARγ and decreases that of tumor necrosis factor-α (TNF-α), a cytokine that reduces insulin sensitivity; therefore, it is expected to improve insulin resistance in clinical settings." (PMID 30943275, 2019). "In this context, phosphorylation of the serine residue S273 in PPARγ LBD was identified as a link between obesity and insulin resistance, and its inhibition by PPARγ ligands, such as TZDs, was directly related to their antidiabetic effects." (PMID 29449830, 2018). "Transgenic mice with adipose-specific overexpression of PPARγ display obesity and increased global insulin sensitivity, and are protected against high fat diet (HFD)-induced insulin resistance and hyperglycemia." (PMID 28515350, 2017). "CCDC3 alleviates glucose intolerance, insulin resistance and steatosis formation in transgenic CCDC3 mice on high-fat diet (HFD) by reducing the expression of hepatic PPARγ and its target gene CIDEA as well as other genes involved in de novo lipogenesis." (PMID 28827783, 2017).
Insulin resistance (continued). "PPARγ activation results in reduced expression of factors such as TNF-alpha, IL-1 and resistin which are insulin resistance-inducing adipokines." (PMID 28243251, 2017). "Among the genes involved in the development of insulin resistance are the ADAM metallopeptidase with thrombospondin type 1 motif 9 (ADAMTS9), glucokinase regulator (GCKR), and peroxisome proliferator activated receptor gamma (PPARG) genes." (PMID 28225792, 2017). "Another dominant negative PPARγ (L466A) mouse model shows lipodystrophy, increased FFA levels, liver steatosis, hypertension and develops mild insulin resistance, when fed with high-fat diet." (PMID 27483259, 2016). "Other compounds that regulate glucose homeostasis, including the PPARγ activator rosiglitazone, might also synergize with rapamycin; rosiglitazone was recently shown to normalize fasting hyperglycemia and attenuate rapamycin‐induced glucose intolerance and insulin resistance in rats." (PMID 27312235, 2016). "The peroxisome proliferator- activated receptor-γ (PPARγ) is a clinically validated target for T2DM treatment and its agonists are clinically used to improve insulin resistance and counteract hyperglycemia." (PMID 27391974, 2016). "In clinical and animal studies, rosiglitazone and pioglitazone, two PPARγ-selective agonists, have been reported to improve NAFLD and insulin resistance." (PMID 27907035, 2016). "Tregs in VAT express peroxisome proliferator-activated receptor gamma (PPAR-γ), a transcription factor that is required for the accumulation of Tregs at this location where they have a positive effect on insulin resistance and glucose metabolism." (PMID 26834735, 2015). "Some angiotensin receptor blockers (ARBs) have a beneficial effect on insulin resistance and T2DM, owing to their action on the renin-angiotensin system and partial agonist activity at PPARγ, an important regulator of adipocyte function." (PMID 26474943, 2015). "Treatment with glitazones, peroxisome proliferator-activated receptor gamma (PPAR-γ) agonists, was shown not only to improve insulin resistance and glycemic control, but also to decrease arterial stiffness in patients with type 2 diabetes mellitus." (PMID 25170513, 2014). "The peroxisome proliferator-activated receptor gamma (PPARG), Pro12Ala and the insulin receptor substrate (IRS1), Gly972Arg confer opposite effects on insulin resistance and type 2 diabetes mellitus (T2DM)." (PMID 24447396, 2014). "In this review, mechanisms involving free fatty acids, adipocytokines such as TNFα and PPARγ and serine kinases like JNK and IKKβ, asserted to be responsible in the development of insulin resistance, will be discussed." (PMID 24324517, 2013). "Although cells expressing the HCV core 1b had reduced IRS-1content and insulin resistance, the effect seemed to be mediated by both SOCS-and PPARγ-independentmechanisms." (PMID 19132131, 2009). "The PPARγ agonist rosiglitazone increased plasma level of adiponectin, decreased fasting plasma glucose and HBA1C, and ameliorated insulin resistance in type 2 diabetic patients." (PMID 15491498, 2004). "Studies have demonstrated that berberine enhances lipid metabolism, lowers LDL-C, TG, and TC levels, improves insulin resistance and oxidative stress, and exerts anti-inflammatory effects through the inhibition of TNF-α and IL-6 secretion, as well as modulation of the PPARγ signaling pathway." (PMID 41304686, 2025). "Gut microbiota metabolites may exert therapeutic effects on insulin resistance primarily through the targets IL6, JUN, and PPARG." (PMID 40625623, 2025). "Therefore, these compounds have been reported to reverse insulin resistance, regulate GLUT4 expression and translocation, and increase peroxisome proliferator-activated receptor gamma (PPARγ)." (PMID 41300019, 2025).
Insulin resistance (continued). "Fasting might also improve insulin resistance via upregulation of PLIN4 (Perilipin 4) expression, triggering similar effects as PPAR-γ (Peroxisome proliferator-activated receptor gamma) activators (e.g., pioglitazone)." (PMID 39545228, 2024). "Fetuin-A is thought to contribute to insulin resistance through multiple mechanisms, including impairment of insulin receptor signaling, inhibition of GLUT-4 translocation, and reduction in PPARγ and adiponectin expression, as shown in obese insulin-resistant mice." (PMID 39409124, 2024). "In addition, it has been observed that the PPARγ inhibitor GW9662 can ameliorate high-fat-diet-induced fatty liver and insulin resistance." (PMID 38276299, 2024). "Rosiglitazone and pioglitazone, members of the thiazolidinediones (TZDs), are classical drugs that have traditionally been used to treat insulin resistance in T2DM, and the effects of the two drugs have been mediated through binding the PPARγ and have acted as an agonist of PPARγ." (PMID 38254542, 2024). "It is known that MAPKs and NF-κB, activated by tumor necrosis factor-α (TNF-α), reduce insulin signaling, arouse inflammatory responses and interfere with peroxisome proliferator-activated receptor gamma (PPAR-γ) activity, leading to insulin resistance and adipose dysfunction." (PMID 39125686, 2024). "Recent studies have shown that PPARγ can induce the expression of adipose-related factors FGF1 and FGF21, members of the fibroblast growth factor family, which are able to maintain adipose homeostasis and counteract insulin resistance." (PMID 39199386, 2024). "Finally, MAFLD-related metabolic disorders, such as insulin resistance, diminish HBV replication by suppressing the activity of peroxisome proliferator-activated receptor-gamma (PPAR-γ) coactivator one alpha." (PMID 38243304, 2024). "ADPQ has been found to have the ability to reduce insulin resistance (IR) through the activation of specific proteins, such as adenosine monophosphate-activated protein kinase (AMPK) and peroxisome proliferator-activated receptor gamma (PPAR-γ)." (PMID 37767256, 2023). "The remaining loci were associated with ISI, including 6 loci not previously implicated in post-challenge insulin resistance: MTOR, COBLL1, PPARG, C5orf67, FAM101A, SLC2A4." (PMID 37291194, 2023). "Additionally, morusin plays a role in amending insulin resistance of hepatocytes by repressing the expression of the ADORA1 and PPARG genes." (PMID 36278175, 2022). "It has been reported that Treg cells lacking PPAR-γ exhibited a phenotype of insulin resistance, and the PPARγ agonist pioglitazone failed to restore its insulin sensitivity in Treg-specific PPARγ-/- mice." (PMID 36032141, 2022). "The cellular assay based on phenotypic differentiation, rather than direct activation of PPARγ, was the best predictor of activity in the animal models of insulin resistance, which included KKAy mice, ob/ob mice, db/db mice, and mice fed a high fat diet." (PMID 34863942, 2022). "In the current study, the low-dose albendazole treatments may decrease the insulin resistance and hyperlipidemia through AMPK, PPARγ, and other pathways." (PMID 33641315, 2021). "We suggest that this does not lead to attenuated PPARγ activity and insulin resistance because roscovitine can also inhibit ERK activity." (PMID 34645915, 2021). "Therefore, future studies on the effects of CJHE in the PPARγ expression and insulin sensitivity in the differentiated adipocytes will be also critical to determine utility of CJHE for insulin resistance and diabetes." (PMID 33804020, 2021). "It was shown that insulin resistance and inflammation reduce the ability of ASC to differentiate into mature adipocytes by suppressing PPARγ and insulin signaling pathway, leading to adipocyte hypertrophy in order to meet the demand for increased triglyceride storage." (PMID 33536069, 2021).